VEGFA (vascular endothelial growth factor A)
Diseases named in the same sentence as VEGFA in open-access papers (continued):
Sharing a sentence is not in itself a finding about the gene and the disease.
tumor (continued). "Hypoxia can stimulate tumor cells to secrete vascular endothelial growth factor A (VEGFA) that binds to VEGF receptor 2 (VEGFR2) on neighboring vascular endothelial cells, thereby inducing the motility of endothelial cells and remodeling of ECM." (PMID 38646439, 2024). "CB-NPs can reduce the expression of VEGFA and restrain tumor angiogenesis to impede tumor progression." (PMID 38375454, 2024). "Tumor cells and stromal-derived VEGFA prompts endothelial cell growth, new blood vessel formation, and tumor progression." (PMID 38047300, 2024). "Here, we show marked increase in VE-cadherin fragmentation indicative of increased VE-cadherin dynamics in initial lymphatic vessels in the ear dermis in the presence of a tumor and in response to VEGFA or VEGFC treatment." (PMID 38148112, 2024). "Vascular Endothelial Growth Factor A (VEGFA) is highly expressed in tumor tissues and induces angiogenesis." (PMID 37925811, 2024). "Endothelial Snai1 inhibition improved the tumor vasculature, with respect to all three parameters—a stark contrast to anti-VEGFA therapy that only improves vessel maturation but often reduces the already critical vessel density even further." (PMID 39095583, 2024). "Crosstalk between the major angiogenic growth factor VEGFA and integrin cell adhesion receptors has recently emerged as a critical factor in regulating angiogenesis and tumor development." (PMID 38321003, 2024). "The crucial role of the TMEM is VEGFA-dependent disruption of endothelial cell-to-cell adhesions, transient vascular leakiness and tumor cell intravasation." (PMID 39516356, 2024). "The functional assessment of MDSCs through the analysis of PTGS2, S100A8, IL10, TGFB1, and VEGFA expression provides a comprehensive view of their immunomodulatory activities within the tumor microenvironment." (PMID 39916959, 2024). "This process is mediated by the release of vascular endothelial growth factor A (VEGFA) from S100A4-positive/hypoxia-inducible factor-1α (HIF-1α)-positive tumor cells." (PMID 39273383, 2024). "miR-134 was a tumor suppressor by targeting VEGFA (vascular endothelial growth factor)/VEGFR1 (vascular endothelial growth factor receptor 2) signaling to attenuate the progression and angiogenesis in osteosarcoma." (PMID 38743209, 2024). "Tumor angiogenesis is known to be regulated by VEGFA and VEGF receptors, such as VEGFR2, in TNBC subtypes." (PMID 38315147, 2024). "For CD14+ monocytes, the VEGFA/PGF-VEGFR1 axes play a significant role in tumor angiogenesis, which is related to a poorer prognosis." (PMID 38600248, 2024). "This acetylation fosters the formation of tumor-specific SEs at the loci of genes that boost angiogenesis (e.g. VEGFA, angiopoietins), facilitating tumor growth and vascular development." (PMID 38844984, 2024). "This interaction led to increased VEGFA expression in cancer cells, thereby promoting angiogenesis and tumor growth 61-63." (PMID 39247606, 2024). "Since miR-424 can influence expression of VEGFA, it has a pivotal role in the regulation of tumor angiogenesis." (PMID 37178445, 2024). "The literature indicates an important function for VEGFA in the regulation of the tumor immune microenvironment." (PMID 38169627, 2024). "Tumor cells also induce the expression of FasL in endothelial cells via vascular endothelial growth factor-A (VEGF-A), IL-10, and prostaglandin E2 (PGE2), thereby eliciting specific cytotoxic effects in effector T cells." (PMID 38840908, 2024). "The group administered with a high concentration (100 mg/kg) of garlic peel extract demonstrated a significant inhibition of CD31 and VEGFA expression in 4T1 tumor tissues." (PMID 39554336, 2024). "EG00229 has anti-tumoral activity in different tumours, inhibiting NRP1-dependent endothelial and tumour cell migration downstream of VEGFA." (PMID 38323651, 2024).
tumor (continued). "Many tumor cells express high levels of VEGFA and its receptors/co-receptors; thus, bevacizumab can theoretically exert direct cytotoxic effects on these cells by blocking VEGFA." (PMID 38716237, 2024). "This antibody also directly binds to VEGFA-expressing tumor cells, thereby triggering apoptosis pathways and inhibiting proliferation and survival signaling." (PMID 38716237, 2024). "In-depth rescue experiments illuminated that the promoting role of PHF5A on tumor progression was dependent on the intact VEGFA expression." (PMID 38429756, 2024). "HCC tumor cells are a well-known source of VEGFA,14, 18 yet several immune cells have been identified as alternate sources of VEGFA." (PMID 39761010, 2024). "In primary tumors, perivascular TAMs mainly express TIE2 and VEGFA and activate leukocyte recruitment and regulation, facilitate the intravasation of tumor cells, promote angiogenesis, and support tumor relapse after chemotherapy." (PMID 39516356, 2024). "CCR5 induces vascular endothelial growth factor A (VEGF-A) expression to promote angiogenesis and recruits immunosuppressive tumor-associated macrophages (TAMs) and myeloid-derived suppressor cells (MDSCs)." (PMID 39199569, 2024). "Research has increasingly demonstrated that JAK/STAT3 participates in tumor angiogenesis, particularly in the regulation of VEGFA." (PMID 39596828, 2024). "This process is regulated by various factors within the tumor microenvironment, with Vascular Endothelial Growth Factor A (VEGFA) originating from tumor cells playing a particularly significant role through paracrine signaling." (PMID 39532855, 2024). "Among them, Vascular endothelial growth factor A (VEGF-A) is a major mediator of tumor angiogenesis and induces angiogenesis through direct action on endothelial cells." (PMID 38375031, 2024). "Taken together, these data preliminary indicated tumor cell-derived VEGFA participated in polarization of macrophages and contributed to the formation of immune supression microenvironment in TNBC." (PMID 38169627, 2024). "Together, the mIHC, scRNA-seq, and spatial transcriptomic data reveal that tumor regions are not only highly enriched with CD34+ tumor endothelial cells, but also have VEGFA+ PVM that interact with these endothelial cells in that region." (PMID 39761010, 2024). "This heterogeneity creates a complex matrix in the tumor environment mainly focused on tissue remodeling by producing MMPs, VEGFA, and FAP." (PMID 39511139, 2024). "Surprisingly, MCM3 was positively correlated with the expression of several immune checkpoint molecules, such as HMGB1, BTN3A2, CD276, and VEGFA, in almost all of the tumours." (PMID 38698811, 2024). "Bevacizumab is a humanized anti-VEGF monoclonal antibody, which can inhibit tumor angiogenesis by binding with VEGFA and inhibiting its binding with vascular endothelial growth factor receptor (VEGFR)-2." (PMID 38167076, 2024). "Tumor-derived VEGFA, IL-10 and prostaglandin E2 cooperatively induce upregulation of the death mediator Fas ligand (FasL) in ECs which gain the ability to kill effector CD8+ T cells but not Treg cells (due to expression of FoxP3)." (PMID 38426109, 2024). "Nevertheless, this culture system was utilized to identify a potential mechanism via which myeloid cells, specifically DCs, become dysregulated and twisted to support tumor progression by secreting VEGFA and MMPs." (PMID 39211033, 2024). "Immune-vascular cross-talk underpins the rationale for using bevacizumab, an anti-VEGFA monoclonal antibody that normalizes tumor vasculature, in conjunction with immune checkpoint inhibitors in advanced unresectable HCC." (PMID 39761010, 2024). "VEGFA exhibited upregulation in the tumour area with immune exclusion, stimulating angiogenesis and facilitating tumour growth and metastasis." (PMID 39187937, 2024). "We further investigated the expression of 10 key genes in NSCLC cell subtypes, among which EGFR and VEGFA are significantly enriched in tumour cells." (PMID 38801409, 2024).
tumor (continued). "HIF1α can transcriptionally activate several proangiogenic factors, such as VEGFA, which promotes the formation of new blood vessels to enhance oxygen delivery to tumor cells and facilitate their growth." (PMID 39532855, 2024). "Flt-1 is the type 1 receptor for vascular endothelial growth factor A (VEGF-A) and a key modulator of tumor angiogenesis." (PMID 39170516, 2024). "We found that under hypoxic tumor conditions, abundant VEGFA is released, generating 2 distinct tumor immuno-angiogenic ecosystems in male patients when stratified based on high or low ESR1 expression." (PMID 38411438, 2024). "We also detected the expression of KI-67, CD31, and VEGFA using IHC staining in tumour masses in order to assess the degree of tumour angiogenesis and neoplastic malignancy." (PMID 38981872, 2024). "Exposure of initial dermal lymphatics to VEGFA or a tumor results in zippering of VE-cadherin at junctions, concomitant with Src-dependent VE-cadherin fragmentation." (PMID 38148112, 2024). "In 1993, a monoclonal antibody targeting and neutralizing VEGFA was identified to inhibit tumor growth in xenograft models, which opened translational avenues for targeting VEGF-VEGFR signaling." (PMID 39576764, 2024). "In line, PIE increased VEGFA expression, indicating the activation of angiogenesis at tumor locations (P < 0.01)." (PMID 38554175, 2024). "By binding to VEGFR2 to increase endothelial cell proliferation via the RAS-RAF-MAPK-ERK signaling pathway, VEGFA appears to be the major mediator of tumor angiogenesis." (PMID 38339258, 2024). "Robustaflavone (RF) is a natural biflavonoid compound that inhibits VEGFA stimulated blood vessel formation in CT-26 cell-derived mice tumor models." (PMID 38687357, 2024). "The expression of VEGFA mRNA and protein in tumour tissues and HCC cells (HepG2, HepG3B, Huh7, SNU‐449 and PLC) was significantly higher than that in adjacent tissues and normal liver cells (L02) by PCR and Western blotting." (PMID 36729917, 2023). "Neutrophils were reported to produce cytokines like VEGFA which promotes tumor angiogenesis and tends to suppress lymphocytes-mediated cytolysis of cancer cell." (PMID 37215452, 2023). "Interleukin-6 (IL-6) plays a role in hormone release, tumor growth and proliferation, and the production of angiogenic factors, particularly vascular endothelial growth factor-A (VEGF-A)." (PMID 38275385, 2023). "Evidence has been provided that vascular endothelial growth factor A (VEGFA)-targeted agents such as bevacizumab promote intra-tumoral hypoxia through blocking tumor angiogenesis." (PMID 37540301, 2023). "For tumor-derived cluster 6, a high expression level of VEGFA and a strong hypoxia signal supported that cluster 6 played an important role in promoting angiogenesis." (PMID 37644609, 2023). "Patients with tumor tissues presenting moderate/strong VEGFA staining intensity, or over 50% VEGFA-positive cells, showed a longer period without recurrence after bevacizumab treatment (PFS-2)." (PMID 37190125, 2023). "VEGFA is another essential modulator that induces angiogenic cascades, which have been proven predominantly in tumor models." (PMID 37008067, 2023). "The role of MMP-2 and MMP-9 in the degradation of ECM significantly contributes to tumor invasion and the aggressiveness of GBs, while the aberrant expression of VEGFA is suggested to drive angiogenesis and tumorigenesis." (PMID 37190125, 2023). "For mechanism of STK24 action, it was evident that STK24 prevents STAT3 from polyubiquitin–proteasomal–mediated degradation and STK24 regulated tumor angiogenesis through STAT3/VEGFA signaling pathway." (PMID 36720310, 2023). "Among the five tumor cell clusters, we found that ITGA5 and VEGFA were coexpressed in tumor clusters (C0‐C4), C0/C2 and C1/C3 were predominant in HPV‐positive and HPV‐negative tumors, respectively." (PMID 36999964, 2023).
tumor (continued). "Studies have shown that circ-001971 as a ceRNA attenuated miR-29c-3p-induced VEGFA inhibition and affected endothelial cell angiogenesis through the tumor microenvironment, thereby aggravating CRC proliferation, invasion, and angiogenesis." (PMID 37587207, 2023). "Vascular endothelial growth factor A (VEGF-A) plays pivotal roles in regulating tumor angiogenesis as well as physiological vascular function." (PMID 37027444, 2023). "In contrast to miR-21, miR-126 acts as a tumor suppressor in tumor tissue, e.g., by targeting ROCK1 (Rho-Associated Coiled-Coil Containing Protein Kinase 1) and VEGFA (Vascular Endothelial Growth Factor A)." (PMID 37046643, 2023). "In vitro xenograft tumor assays confirmed that STK24 can positively administer STAT3/VEGFA signaling pathway." (PMID 36720310, 2023). "The higher expression of VEGFA in tumours with higher T stage and pathologic stage suggested that angiogenesis is an important factor in tumour growth and progression." (PMID 36729917, 2023). "M2 macrophages also produce EGF and vascular endothelial growth factor A (VEGFA) to promote tumour growth and angiogenesis." (PMID 37612278, 2023). "As for VEGFA, it is an important mediator of vascular development such as angiogenesis, meanwhile angiogenesis is a pivotal event in tumor progression." (PMID 38035023, 2023). "This potential is attributed to its ability to regulate the SP1/miR-125b-5p/VEGFA pathway, thus suppressing the expression of VEGF and limiting tumor blood vessel formation." (PMID 38035069, 2023). "The potential regulatory mechanism is associated with some critical signaling molecules involved in tumor metastasis, invasion, and matrix reconstruction, such as vascular endothelial cadherin (VE‐cadherin), VEGFA, EphA2, PI3K/AKT signals, MMPs, and HIF‐1α." (PMID 36708044, 2023). "Vascular endothelial growth factor A (VEGFA) is a potent angiogenic factor involved in tumor progression." (PMID 37183363, 2023). "The results of the current study revealed that STK24-mediated tumor angiogenesis was dependent on STAT3/VEGFA signaling pathway." (PMID 36720310, 2023). "Based on these results, we extended the search for possible predictive markers by assessing the copy number status of the VEGFA gene as well as its expression in tumor tissue." (PMID 37893095, 2023). "This invasive form of p-FoxM1 upregulates the expression of IL1A/1B, VEGFA, and IL6 by direct activation, recruiting monocytes and promoting the polarization of M2d-like tumor-associated macrophages (TAMs)." (PMID 37968723, 2023). "As GBM is a hyperemic tumor involving the upregulation and activation of VEGFA and HIF, VEGFA is a reasonable target molecule in the treatment of GBM." (PMID 37316802, 2023). "VEGFA expression is elevated in multiple tumour types and correlates with the prognosis of tumour patients." (PMID 36729917, 2023). "VEGFA has been identified as the most potent cytokine involved in tumor angiogenesis and metastasis formation." (PMID 36833207, 2023). "Specifically, the study considered the status of the chromosome 6 locus in VEGFA gene maps and its expression levels in tumor tissues in addition to an analysis of micro-vessel density status." (PMID 37893095, 2023). "In contrast, up‐regulation of VEGFA was enriched into angiogenesis‐related pathways, indicating pro‐tumour effects." (PMID 37491740, 2023). "The VEGFA expression positively correlated with circHIPK2 while negatively correlating with miR-1249–3p expression, as assessed by tumor xenograft studies." (PMID 36900356, 2023). "Here, we have defined a VEGFR2 Y1173/PLCγ/eNOS/Src signaling pathway vital for VEGFA-induced macromolecular leakage in healthy vessels as well as in tumor vessels, of consequence for tumor immune status and disease outcome (see graphical abstract)." (PMID 37651195, 2023).
tumor (continued). "The actively metabolic tumor cells and insufficient blood supply lead to the hypoxic tumor microenvironment, which in turn responds to elevated levels of certain pro-angiogenic factors like VEGFA." (PMID 37573354, 2023). "LncRNA SNHG11 is highly expressed in pancreatic cancer patients, which promotes VEGFA expression by miR-324-3p, thus increasing tumor angiogenesis and facilitating metastasis." (PMID 37369681, 2023). "Increased VEGFA expression at the mRNA level in KIRC tumor samples compared to normal kidney tissues was also found in tissues from a large group of patients (research based on mRNA-sequencing data of KIRC from an online database)." (PMID 37964226, 2023). "In conclusion, the findings of this study demonstrated that STK24-mediated tumorigenesis, and tumor angiogenesis was dependent on STAT3/VEGFA signaling pathway." (PMID 36720310, 2023). "VEGFA growth factor is a pivotal driver in tumor-mediated angiogenesis and is also important in sustaining tumor growth and metastasis formation." (PMID 37893095, 2023). "For example, although vascular endothelial growth factor A (VEGF-A) is an angiogenic factor that supports tumor growth, it is essential for vessel maintenance, indicating a requirement for its basal expression for homeostasis maintenance." (PMID 37779151, 2023). "FGF2 not only recruits various host cells to the tumor microenvironment (TME) but also enhances VEGFA-dependent neovascularization during tumor progression—a process essential for subsequent tumor growth and metastasis." (PMID 36647777, 2023). "Vascular endothelial growth factor A (VEGFA), a potent angiogenic factor, binds to neuropilins in endothelial and tumor cells." (PMID 36942388, 2023). "Tumor cells always activate and initiate angiogenesis by releasing VEGFA to improve their microenvironment in many physiological and pathological conditions, such as hypoxia and high levels of lactate." (PMID 36913368, 2023). "HIF-1α target genes, including GLUT1, HK2, PDK1, PFKFB, and VEGFA, are pivotal in regulating tumor metabolism, metastasis, and angiogenesis." (PMID 37906252, 2023). "TRPS1, a GATA family transcriptional regulatory factor, has been shown to induce tumor angiogenesis, affect VEGFA expression, and promote tumor cell proliferation in tumors." (PMID 37745301, 2023). "VEGFA widely expresses in nearly all cancers and is recognized as the most crucial tumor angiogenesis factor." (PMID 36902812, 2023). "ER stress-induced miR-153 expression in breast cancer cells activates IRE1α and XBP1, which inhibits HIF1α expression and tumor angiogenesis by decreasing VEGFA production." (PMID 36890838, 2023). "Overexpression of VEGFA resulted in increased VEGFA mRNA expression in tumor cells compared to controls, and it reversed the VEGFA reduction induced by miRNA-383-5p transfection." (PMID 37592783, 2023). "Further analysis suggests that the increased MDMs arisen from excessive recruitment and proliferation of peripheral monocytes not only lead to the T cell function inhibition in GBM, but also stimulate tumor cells proliferation via VEGFA secretion." (PMID 36761752, 2023). "Functional inactivation of FBXW7 led to activation of the MAPK signaling pathway and upregulation of the downstream MMP3 and VEGFA, which enhanced tumor proliferation cell invasion and migration." (PMID 36991467, 2023). "The CD14+ERO1A+ TAM cluster, together with two hypoxia-dependent MES-like tumor cells expressed VEGFA, indicating their contribution to the induction of angiogenesis in GBM via interacting with endothelial cells." (PMID 37731483, 2023). "Stimulating signals involved in tumour angiogenesis, like VEGFA–VEGFR2 and VEGFB–VEGFR1, were observed." (PMID 36588094, 2023). "VEGFA serves as a key regulator of tumor angiogenesis, exerting precise control over the migration, proliferation, and vascular permeability of vascular endothelial cells." (PMID 38104099, 2023).